MITF (melanocyte inducing transcription factor)
Diseases named in the same sentence as MITF in open-access papers (continued):
Sharing a sentence is not in itself a finding about the gene and the disease.
tumor (continued). "Moreover, by estimating the frequency of immune cells in the tumor bulk, we found an interesting correlation between MITF and OPN4 with different immune cell types that is suggestive of a role of OPN4 in TME and consequently tumor progression." (PMID 35562405, 2022). "Notably, none of them has been well studied in BC, and our results demonstrated the biological functions and tumor expression of each gene in BC progression, which enriched the research profiles for the MITF/CCDC183-AS1/miR-4731-5p/TCF7L2 axis." (PMID 35957803, 2022). "Thus, we investigated the biological function of MITF and its effect on tumor growth and cancer progression in ccRCC." (PMID 34208068, 2021). "Therefore, these pathways are also likely to be involved in modulating MITF levels and thereby contributing to phenotype switching and tumor heterogeneity in the end." (PMID 34071193, 2021). "Additionally, tumor formation was impaired by MITF knockdown and enhanced by MITF overexpression in vivo." (PMID 34208068, 2021). "Moreover, we showed that MITF promoted cell motility, migration and invasion in vitro, and induced tumor formation in vivo in xenograft models of ccRCC." (PMID 34208068, 2021). "MITF can have both tumor-promoting and suppressive features." (PMID 34071193, 2021). "MITF maintains tumor homeostasis by regulation of cell cycle and suppression of apoptosis." (PMID 33329751, 2020). "The present data reveal that CBP- and SIRT1-driven reversible acetylation of HINT1 at both K21 and K30 affects the capacity of HINT1 to bind to β-catenin or MITF, which, in turn, can influence its tumor-suppressive activity in cancer cell lines and in an in vivo xenograft mouse model." (PMID 32636443, 2020). "This may indicate that WT MITF in the tumor-formation assay may be only partially acetylated, perhaps because the microenvironment after subcutaneous injection is very different from that in development or 501mel cells in culture." (PMID 32531202, 2020). "Indeed, heterogeneous tumours were enriched for EMT and Verfaillie “invasive” signatures even relative to WM266‐4 tumours, but MITF expression was higher than in WM266‐4 tumours." (PMID 32145051, 2020). "Furthermore, an inversely correlated expression of receptor tyrosine kinase AXL compared to MITF has been reported to drive tumor resistance." (PMID 33167306, 2020). "To determine whether MITF expression in tumor cells influenced the progression of OvCa, we performed IHC analysis of MITF in primary OvCa tissue samples." (PMID 33371469, 2020). "We therefore asked whether the cell lines expressing WT MITF or the K243R or K243Q MITF mutants exhibited differential tumor-forming potential following subcutaneous injection into athymic nude mice." (PMID 32531202, 2020). "Expression of MITF and its target genes linked to differentiation and proliferation was up‐regulated in all growing tumours compared to the initially injected cells, which is in line with the requirement of MITF for tumour growth (Simmons, Pierce, Al‐Ejeh, & Boyle, 2017)." (PMID 32145051, 2020). "The detailed characterization of global gene expression profiles and biological processes affected by NRF2 repression in vitro and in vivo allowed us to uncover an important role of NRF2 in tumor growth and immune evasion by regulating the MITF/differentiation as well as the ATF4/COX2 pathways." (PMID 32978520, 2020).
tumor (continued). "While cell lines preferentially adopt either a proliferative or an invasive phenotype, with a clear-mirrored expression of ZEB1 and MITF, tumors in vivo display a higher level of intra-tumor heterogeneity with a significant proportion of cells in the mixed/intermediate state." (PMID 32759677, 2020). "The interaction between the transcription of genes in the tumor and the immune system is also important: depending on the melanoma tumor type, low levels of transcription of a gene called MITF results in fewer immune cells being attracted to the tumor, which leads to an acceleration in tumor growth." (PMID 31169498, 2019). "Within a given tumor cell population the dichotomous behavior of MITF shuttling between low and high expression levels is largely enigmatic, but it may reflect invasive or dormant vs. proliferative states with varying transcriptional demands." (PMID 30651597, 2019). "Moreover, many of the factors de-repressed upon MITF knockdown are important players that activate anti-tumor immunity (e.g. IL15, CCL2), which suggests a potential role of MITF in evasion of immune surveillance." (PMID 31554806, 2019). "Indeed the notion of tumor cell subpopulations is yet deeply investigated at the single-cell level and markers such as MITF or SOX10 have been suggested to identify them." (PMID 31118886, 2019). "Tumors from the mice injected with miR-876-5p-transfected MGC803 cells were smaller than that derived from mimics control-transfected mice; in miR-876-5p and si-WNT5A or si-MITF group, overexpression of WNT5A or MITF mitigated the inhibitory effects of miR-876-5p on tumor size." (PMID 31171711, 2019). "Recent studies have found great heterogeneity in MITF expression within tumours." (PMID 30511391, 2019). "Importantly, the MITF–GTF2H1 axis is preserved in MITF-abundant melanomas with potential implications for primary tumor progression and macro-metastatic disease." (PMID 30651597, 2019). "Moreover, the novelty of our study relies on the observation and definition of the tumor-suppressive activity of MITF in PCa." (PMID 30310055, 2018). "The observed low‐MITF/high‐Axl populations in sections of human tumours 22 could serve as a possible example." (PMID 29369499, 2018). "Our data provide solid evidence of an unprecedented MITF-CRYAB transcriptional axis that exerts tumor-suppressive activity in PCa and could positively contribute to disease prognosis." (PMID 30310055, 2018). "It is questionable whether the increase in p27 protein alone can incur the deceleration of proliferation in all types of low‐MITF cell lines and tumours subpopulations." (PMID 29369499, 2018). "First, apparently, highly different cell context may exist among tumour cell subpopulations, and possibly single cells, that ensure antiapoptosis within the low‐MITF cells." (PMID 29369499, 2018). "Importantly, the tumor-suppressive role for this novel MITF-CRYAB axis is supported by the enhanced prognostic potential of a signature based on the concomitant alteration of both genes in PCa patients." (PMID 30310055, 2018). "In addition, not only the mean expression but also the expression of the individual MITF isoforms were reduced in primary tumor specimens when compared with the normal prostate tissue samples." (PMID 30310055, 2018). "Thus, our results suggest that MITF levels regulated by NFIB downstream of BRN2 are key in tumour formation and growth." (PMID 28119061, 2017). "Because on BRAF inhibitor monotherapy tumour growth had resumed despite ERK being still inhibited, we wanted to see whether these MITF‐high tumours are enriched for AXL‐high cell populations." (PMID 28606996, 2017). "In this context, stable over-expression of NFIB limits the ability of these cells to upregulate vital components such as MITF, that may be required for the cells to adapt to changes in the local microenvironment in order to establish tumours." (PMID 28119061, 2017).
tumor (continued). "Even within MITF‐high melanomas MITF displays considerable heterogeneity in its expression, whereby cells expressing higher and lower levels of MITF are found within one tumour and located adjacent to each other." (PMID 28606996, 2017). "Possibly, in this in vivo situation stroma‐derived signals from the local tumour microenvironment could have differing effects on MITF expression." (PMID 28606996, 2017). "Taken together, these results show that MITF plays a crucial role in primary tumor growth." (PMID 28883623, 2017). "Intriguingly, MITF heterogeneity can be detected throughout progression and can even be found in circulating tumour cell clusters, suggesting that maintaining heterogeneity throughout tumour progression is beneficial for the establishment of advanced disease." (PMID 28606996, 2017). "The tumor cells displayed transcriptional heterogeneity (i.e., tumors characterized by high levels of the MITF transcription factor also contained cells with low MITF and elevated AXL kinase) associated with the cell cycle, spatial context, and a drug-resistance program." (PMID 29156643, 2017). "Finally, the clinical implications were investigated by comparing the expression profiles of SOX5, SOX10 and MITF to clinically relevant parameters (overall survival and tumor stage), leading to a biomarker regression model (of SOX5, SOX10 and MITF)." (PMID 26927636, 2016). "For instance, the MITF‐centred EMT‐like concept of ‘phenotype switching’ proposes that tumour progression and heterogeneity are driven by dynamic reversible transitions between cell states, which are defined by the ‘proliferative’ and ‘invasive’ gene expression signatures." (PMID 25818589, 2015). "However, in a heterogeneous tumour, the situation is more complex and MITF's role in metastasis awaits further elucidation." (PMID 25818589, 2015). "Pretreatment leading to the generation of cells with suppressed MITF expression appears to enhance tumour initiation, when eventually MITF expression can recover, while continuous suppression of MITF is incompatible with tumour growth." (PMID 25818589, 2015). "The increase in MITF and the genes in its pathway found in 2.17-mAlb treated animals may indicate more differentiated and less progressive tumor." (PMID 24587106, 2014). "Correct classification of these distinct neoplasms is important as the MiTF/TFE3-related cellular pathways may eventually provide targets for novel therapeutic agents." (PMID 24735727, 2014). "Interestingly, MITF regulates the expression of these proteins, reinforcing our observations that cells expressing low levels of MITF correspond to tumor-initiating cells." (PMID 24416617, 2013). "Indeed, MITF represents a transcription factor which regulates melanomagenesis and tumor formation, and is an essential regulator of melanocyte proliferation and differentiation." (PMID 24098663, 2013). "Thus, MITF has both tumour promoting and tumour inhibitory activities and its ability to control cell fate decisions appears to depend on it levels of expression or possibly its levels of activity." (PMID 18628967, 2008). "Furthermore, studies have shown that in melanoma, upregulating TYRO3 to limit tumor ferroptosis promotes resistance to α-PD-1/PD-L1 immune checkpoint inhibition, while enhancing tumor ferroptosis by targeting the Wnt/β-catenin-MITF pathway can improve the efficacy of anti-PD-1 immunotherapy." (PMID 40169575, 2025). "Furthermore, the range of MITF expression levels that define specific tumor phenotypes may also vary between cells." (PMID 40458894, 2025). "Although elevated MITF expression did not achieve statistical significance, its odds ratio (OR = 1.335) exceeded 1, suggesting a potential trend toward association with higher tumor stage." (PMID 41114928, 2025). "Notably, MITF appears to play a crucial role in tumor progression and therapy resistance." (PMID 40647405, 2025).
tumor (continued). "Nevertheless, the striking similarity between ACTIN::MITF-rearranged tumors and PEComas is intriguing and raises a question whether ACTIN::MITF tumors represent a standalone entity, a distinct subtype of PEComa or whether ACTIN::MITF fusions may be shared by two different tumor types." (PMID 39264472, 2024). "It was revealed that systemic targeting of MITF by nelfinavir led to a prominent delay of tumor growth, and targeting MITF was capable of potentiating the treatment influence of anti-PD-1 antibodies that could be reversed by liproxstatin-1, as was revealed by both tumor weight and tumor volume." (PMID 36429010, 2022). "Moreover, the detection of circulating tumor cells with MITF/AXL bias might help optimize prognosis and treatment." (PMID 35054460, 2022). "Besides, the stroma of MITFhigh tumors consisted of a smaller number of cancer-associated fibroblasts and the tumors showed a higher T cell infiltration, suggesting that the composition of the tumor microenvironment (TME) is different depending on MITF expression levels." (PMID 34071193, 2021). "Additionally, short-term MITF depletion downregulates the diaphanous-related formin 1 (DIA1), leading to a p27-dependent cell cycle arrest and increases rho-associated coiled-coil containing protein kinase (ROCK)-dependent invasiveness of the cells, indicating a tumor-promoting role of MITF." (PMID 34071193, 2021). "We examined whether MITF knockdown and MITF overexpression affect tumor growth in vivo." (PMID 34208068, 2021). "Note that whereas in the zebrafish assay or cells in culture, the similar behavior of the WT and K243Q mutant suggests functional MITF may be highly acetylated, in the tumor-formation assay, WT MITF has an intermediate phenotype between the K243R and the K243Q mutants." (PMID 32531202, 2020). "According to the rheostat model proposed by Goding, high MITF expression maintains differentiated status of melanocytes, intermediate MITF expression sustains proliferation, while low MITF levels generate invasive and slow-proliferating cells with tumor-initiating properties." (PMID 32759677, 2020). "Moreover, MITF was reported to upregulate the expression of BCL-2 in tumor cells." (PMID 31333673, 2019). "In sum, mechanisms of drug resistance are numerous and distinct subpopulation of resistant cells with either high SOX10 and high MITF expression or low SOX10 and low MITF expression may exist in the same tumor, rendering difficult to completely eliminate the tumor with one targeted treatment." (PMID 31118886, 2019). "Furthermore, because signals from the tumour microenvironment can influence MAPK signalling the dynamic regulation of MITF downstream of BRAF might explain at least in part the significant heterogeneity in MITF expression that is observed in human tumours." (PMID 30277012, 2019). "However, tumours with both BRAF mutation and MITF activation were more sensitive to PLX4720 compared to tumours with BRAF mutation but without MITF activation." (PMID 29950679, 2018). "Furthermore, we observed that tumours with both BRAF mutation and MITF activation were more sensitive to BRAF inhibitors compared to tumours with BRAF mutation without MITF activation." (PMID 29950679, 2018). "Thus, aberrant SUMOylation of MITF promotes tumor initiation and progression." (PMID 30065750, 2018). "Because melastatin, a MITF transcriptional target and a putative tumour suppressor, is sharply responding to MITF levels in melanocytes 36, we used real‐time PCR to estimate the mRNA levels of melastatin, together with determining the mRNA levels of the bona fide MITF target tyrosinase." (PMID 29369499, 2018). "It has been hypothesized that this variant influences the binding of certain critical transcription factors with tumor-suppressing potential, including microphthalmia transcription factor (MITF), which activates INK4A, a tumor suppressor that inhibits cell cycle progression." (PMID 29599126, 2018).
tumor (continued). "Although MITF expression correlates with the invasiveness of individual cell populations, the cooperative invasion observed in heterogeneous xenografts suggested that both MITFhigh and MITFlow cells could contribute to tumor invasion." (PMID 25066122, 2014). "We also performed IHC staining of 30 pairs of GC tissue sections, and found that the expression levels of METTL10, MITF, and PIAS3K442‐methyl were higher in tumor tissues compared to matched adjacent normal tissues." (PMID 41114928, 2025). "Finally, we note that the MITF KO tumors, unlike any other, exhibited a different structure with large gaps between clusters of tumor cells that may reflect differential cell-cell adhesion or extracellular matrix composition in the MITF KO cells, consistent with a previous report." (PMID 41275493, 2025). "Transcriptomic profiling following MITF silencing further demonstrated enrichment of differentially expressed genes in PI3K/ mTOR signaling, with downstream effects on tumor growth and autophagy." (PMID 41168571, 2025). "miR-182 promotes tumor growth and invasion by the potential target of APC and tumor suppressors like MITF." (PMID 40282456, 2025). "When we categorized the tumor samples into low METTL10 and high METTL10 groups based on METTL10 IHC scores, we again observed significantly higher levels of PIAS3K442‐methyl and MITF in the high METTL10 group." (PMID 41114928, 2025). "MITF knockdown in CCS cells results in decreased cell viability and proliferation, underscoring its crucial role in promoting tumor growth." (PMID 41168571, 2025). "Among these, clusters 0, 1, 2, 3, and 7 are tumor cells that highly express MLANA, MITF, SOX10, and MKI67." (PMID 40356756, 2025). "Stresses promoting an MITF-to-TFEB-to-TFE3 switch will lead cells to suppress proliferation, reprogram metabolism, and impact tumor immune cell infiltration quantitatively and qualitatively." (PMID 41275493, 2025). "Collectively, our results identify MITF as a key regulator of GIST biology, highlighting its potential as a therapeutic target to limit tumor growth and metastasis." (PMID 41168571, 2025). "Tumor sections from PTX-treated groups exhibited a stronger fluorescence signal, corresponding to MITF expression." (PMID 40806647, 2025). "Subcutaneous transplantation into C57BL/6 mice revealed that tumor formation by the MITF/TFE family single KOs and DKOs was delayed, with the MITF KO and the DKOs being most affected." (PMID 41275493, 2025). "By binding the MITF promoter, TFPI2 represses its transcription, reinforcing its tumor-suppressive function." (PMID 40361374, 2025). "Then, we measured the expression levels of MITF, BRAF and NRAS in the annotated cell types, which revealed increased expression of the two former genes in the tumour cells, compared to the microenvironment." (PMID 41168392, 2025). "The complexity of these regulatory networks is further illustrated by the finding that Notch signaling activation leads to MITF‐mediated de‐repression of the MIR222/221 cluster, which inhibits GRB10 and ESR1, ultimately promoting tumor invasion." (PMID 40458894, 2025). "Tumor growth was monitored, and molecular analyses included RNA sequencing and immunofluorescence quantification of PI3K, AKT1, mTOR, ERBB2, BRAF, and MITF protein levels, and molecular docking simulations were performed." (PMID 40806647, 2025). "The regulon specificity score (RSS) highlighted unique regulons across the three studied regions, with MITF(+), PRDM1(+), MAX(+), TFEC(+), and BHLHE41(+) emerging as the most specific regulons within the tumor core." (PMID 38938448, 2024). "This disruption not only aligns with the typical cytoplasmic characteristics but also explains the tumor’s positive immunohistochemical staining for TFE3 and wild-type MITF, as lysosomal inhibition activates the transcription factors MITF, TFE3, and TFEB." (PMID 39372871, 2024).